ANKMY1 (ankyrin repeat and MYND domain containing 1)
Synonyms: ZMYND13; FLJ20499
Tractability: No criterion of Open Targets' tractability assessment is met for any kind of drug.
Gene: Protein-coding gene on chromosome 2 (240,479,422 to 240,569,209, reverse strand). Ensembl gene ENSG00000144504.
Subcellular location (Human Protein Atlas): Nuclear bodies; Nucleoplasm; Cytosol
Genetic constraint (gnomAD): Loss-of-function variants: 100 observed, 103.48 expected, observed/expected ratio (o/e) 0.97, 90% interval 0.82 to 1.14. The upper end of that interval is the gene's LOEUF score, 1.14, which puts it in group 5 of 6, group 1 being the genes least tolerant of losing a copy. Missense variants: 1,330 observed, 1,376.9 expected, observed/expected ratio (o/e) 0.97, 90% interval 0.92 to 1.01. Synonymous variants: 582 observed, 576.11 expected, observed/expected ratio (o/e) 1.01, 90% interval 0.94 to 1.08.
Homologues: Orthologues: chimpanzee ANKMY1 (98% identical), macaque ANKMY1 (89% identical), dog ANKMY1 (68% identical), pig ANKMY1 (67% identical), mouse Ankmy1 (65% identical), guinea pig ANKMY1 (65% identical), rat Ankmy1 (64% identical), tropical clawed frog ankmy1 (39% identical), zebrafish ankmy1 (17% identical).
Diseases named in the same sentence as ANKMY1 in open-access papers:
ANKMY1 is named in the same sentence as 2 diseases in open-access papers, as found by Europe PMC text mining. Sharing a sentence is not in itself a finding about the gene and the disease. The quoted sentences say what the papers report.
melanoma (1 paper, 2025). A malignant, usually aggressive tumor composed of atypical, neoplastic melanocytes. "In GSE46517, IFFO1, ANKRD10, CLPB, TCAP, and POLG2 displayed high expression, but the expression levels of CHMP4A, ZDHHC11, and ANKMY1 were low in the melanoma group." (PMID 40909968, 2025).
ANKMY1 also shares sentences with these, for which no sentence is quoted: parasite (1 paper).